RASSF10 (Ras association domain family member 10)
Diseases named in the same sentence as RASSF10 in open-access papers (continued):
Sharing a sentence is not in itself a finding about the gene and the disease.
tumor (continued). "As a tumor suppressor in vivo, we wanted to understand the RASSF10 mechanism of regulation and contribution to carcinogenesis." (PMID 32047266, 2020). "RASSF10 methylation increased from primary tumors to cancer cell lines, consistent with the progressive hypermethylation of tumor-suppressors during tumorigenesis." (PMID 31817988, 2019). "RASSF10 is significantly hypermethylated in tumor tissues and cancer cell lines (p = 1.5 × 10−29) but ASPP2 is unmethylated." (PMID 31817988, 2019). "Methylation of RASSF10 occurs across the complete CpG island in tumor tissues and methylation is further increased in cancer cell lines, whereas normal tissues are unmethylated." (PMID 31817988, 2019). "In our study, we wanted to understand the mechanism of regulation of RASSF10 and its contribution to inhibition of growth, migration and invasion as a tumor suppressor." (PMID 31817988, 2019). "Here, we report that the RASSF10 tumor-suppressor is upregulated by TGFβ stimulation in epithelial cells (as well as by cellular density) and associated with a G1 cell cycle arrest restricting cell growth." (PMID 31817988, 2019). "Although there are structural differences between classical and N-RASSFs, RASSF8 and RASSF10 also act as a tumor suppressors while RASSF7 regulates cell growth and apoptosis." (PMID 29108261, 2017). "The mean tumor weight was significantly less in RASSF10-transfected nude mice as compared with the vector control mice (P<0.01)." (PMID 27348267, 2016). "The tumour suppressive effect of RASSF10 was most prominent after 72 h when G0-G1 phase cell numbers were reduced from ca. 75% to 58%." (PMID 26927176, 2016). "To further gain the insights into the tumor suppressive property of RASSF10, we investigated the effect of RASSF10 on migration in QGY7703 and HepG2 Cells." (PMID 27348267, 2016). "RASSF10 acting as a tumor suppressor to inhibit HCC invasion partially mediated by Focal Adhesion Kinase or p38 MAPK to decrease the accumulation of MMP2." (PMID 27348267, 2016). "Matching samples exhibited a strong tumour specific promoter methylation of RASSF10 in comparison to the normal control breast tissue." (PMID 26927176, 2016). "We found a significant RASSF10 promoter methylation of 63% in tumour samples, compared to only 4% of methylation in the normal samples." (PMID 26927176, 2016). "QGY7703 and HepG2 cells stably transfected with RASSF10 or empty vector were injected subcutaneously into nude mice and the animals were closely monitored for tumor growth." (PMID 27348267, 2016). "We found that hypermethylation of the RASSF10 promoter region downregulated its expression in HCC, and that RASSF10 expression is an independent prognostic factor for patient survival and tumor recurrence." (PMID 26701853, 2016). "The tumor volume was significantly lower in RASSF10-transfected nude mice as compared with the vector control mice (QGY7703, P<0.01; HepG2, P=0.012)." (PMID 27348267, 2016). "Collectively, our findings indicate that RASSF10 functions as a tumor suppressor in hepatocarcinogenesis." (PMID 27348267, 2016). "RASSF10 overexpression also potentiates docetaxel-induced tumor cell apoptosis, thereby increasing tumor cell sensitivity to chemotherapy." (PMID 26701853, 2016). "Using pyrosequencing we quantified promoter methylation of RASSF10 for a set of samples and observed a clear tumour specific RASSF10 promoter methylation versus normal matching tissue." (PMID 26927176, 2016). "Our own earlier work pinpointed RASSF10 as a heavily inactivated tumour suppressor in various tumour types." (PMID 26927176, 2016). "In conclusion, we identified RASSF10 as a novel tumor suppressor inactivated by promoter methylation in HCC." (PMID 27348267, 2016). "We found that RASSF10 knockdown in HCC cells led to enhanced migration and invasion, and low RASSF10 expression in HCC was associated with tumor thrombus." (PMID 26701853, 2016).
tumor (continued). "RASSF10 has been reported to be frequently methylated in different malignancies and has been regarded as tumor suppressor." (PMID 25638156, 2015). "RASSF10 has been reported to be frequently methylated in different malignancies and is regarded as a tumor suppressor." (PMID 26124922, 2015). "We found that RASSF10 was methylated in 82.6% (57/69) of human primary HCC and methylation of RASSF10 was significantly associated with tumor size (P < 0.05) and TNM stage (P < 0.05)." (PMID 26124922, 2015). "RASSF10 functions as a tumor suppressor and additionally we demonstrated a possible role in cell differentiation." (PMID 24252868, 2013). "In summary we were able to show different RASSFs like RASSF2, RASSF5C and RASSF10 are tumor specifically methylated at their promoter region in MCC, additional to the earlier reported presence of RASSF1A hypermethylation in MCC." (PMID 24252868, 2013). "The focus of our current work was on RASSF2, RASSF5A, RASSF5C and RASSF10, due to the fact that epigenetic inactivation of these tumor suppressors of the RASSF family was already reported in different cancer types." (PMID 24252868, 2013). "It was reported that depletion of RASSF10 caused SMAD2 phosphorylation and promoted tumor invasion." (PMID 35563709, 2022). "Moreover, we found that epigenetic reduction of RASSF10 levels correlates with tumor progression and poor survival in human cancers." (PMID 31817988, 2019). "Additionally, we analyzed the up- and downstream pathways of RASSF10 that are involved in its tumor suppressive function." (PMID 31817988, 2019). "So far it is known that RASSF10 blocks tumour cell growth in vitro and in xenograft." (PMID 26927176, 2016). "Our study suggests that RASSF10 acts as a tumor suppressor for HCC." (PMID 27348267, 2016). "RASSF10 is a member of the well known tumour suppressor family named RASSF." (PMID 26927176, 2016). "However, low RASSF10 expression was more likely in HCC patients with tumor thrombus (P = 0.001, odds ratio (OR) = 0.119, 95% confidence interval (CI): 0.036-0.397) and hepatocirrhosis (P < 0.001, OR = 0.321, 95% CI: 0.181-0.572)." (PMID 26701853, 2016). "As RASSF10 may serve a tumor suppressor function, reversal of RASSF10 suppression could be a promising approach for HCC therapy." (PMID 26701853, 2016). "Tumor growth was marked diminished with RASSF10 expression, with the mean tumor volumes measured at 28 days being 721.25 ± 55.7 mm3vs 158.17 ± 49 mm3 (P < 0.05), and the weight was 360 ± 25 mg vs 76.67 ± 27.5 mg (P < 0.05) in RASSF10 unexpressed and expressed HCT116 cell xenografts respectively." (PMID 25638156, 2015). "Another well-known tumor suppressor in our top 10 list is RASSF10." (PMID 26039411, 2015). "In summary, we could show that Rassf10 functions as a haploinsufficient tumor suppressor." (PMID 32047266, 2020). "However, we failed to confirm the decrease of RASSF10 was associated with the lymph nodes metastasis or tumor stage in the HCC patients." (PMID 27348267, 2016). "Recently, it has been reported that RASSF10 regulates epithelial cadherin (CDH1) expression, that is a tumor suppressive TGFβ-target and inhibits epithelial-to-mesenchymal transition (EMT)." (PMID 32047266, 2020). "We are now showing that RASSF10 expression inhibits signs of EMT in cancer cell lines, but we are also reporting its mode of action as a tumor suppressor." (PMID 31817988, 2019). "RASSF10 is frequently hypermethylated and down-regulated in HCC, which is correlated with increased tumor recurrence and reduced survival in HCC patients." (PMID 29088763, 2017). "In conclusion, we found that RASSF10 is downregulated in HCC, leading to more aggressive tumor behavior and predicting poor patient outcome after curative resection." (PMID 26701853, 2016). "Transgenic expression of RASSF10 in silenced HCC cell lines suppressed cell viability, colony formation and inhibited tumor growth in nude mice (QGY7703, P<0.01; HepG2, P<0.05)." (PMID 27348267, 2016).
tumor (continued). "To assess the function of RASSF10 in vivo, we overexpressed RASSF10 in MHCC97H cells, implanted these cells into nude mice, and monitored tumor growth." (PMID 26701853, 2016). "To determine whether RASSF10 acts as a tumor suppressor in HCC, we thus examined the growth-suppressive effect through restoration of RASSF10 in QGY7703 and HepG2." (PMID 27348267, 2016). "In this study we analysed the tumour suppressors RASSF1A and RASSF10." (PMID 26927176, 2016). "On the other hand, the epigenetic status of RASSF10 is not fully elucidated in lung cancer and only few studies including experiments with cancer cell lines have shown its activity as a tumor suppression gene in lung tumorigenesis and its implication in cell cycle progression and tumor growth." (PMID 34885084, 2021). "In our study we found a significant epigenetic silencing of RASSF10, but not ASPP2 in different tumor entities." (PMID 31817988, 2019). "In this study, we found RASSF10 was frequently silenced or down-regulated in HCC cell lines and HCC tissues as comparing with their adjacent non-tumor tissues, suggesting RASSF10 would be a potential tumor suppressor in the carcinogenesis of HCC." (PMID 27348267, 2016).
cancer (12 papers, 2009 to 2021). A tumor composed of atypical neoplastic, often pleomorphic cells that invade other tissues. "In combination with other markers, RASSF10 silencing can serve as diagnostic and prognostic cancer biomarker in kidney diseases." (PMID 32047266, 2020). "Our own earlier work implicated RASSF10 in inhibiting cell cycle progression in certain cancer cells upon activation of the cAMP-signalling pathway." (PMID 26927176, 2016). "Methylation of the Ras-association domain family 10 (RASSF10) promoter region correlates with clinicopathological characteristics and poor prognosis in several human cancers." (PMID 26701853, 2016). "Thus, loss of RASSF10 expression by promoter hypermethylation can serve as a diagnostic and prognostic cancer marker." (PMID 31817988, 2019). "In independent datasets we could validate, that loss of RASSF10 expression clinically correlated with decreased survival and with progressed disease state of cancer patients." (PMID 31817988, 2019). "In addition, we can exclude mutation events in the inactivation of RASSF10 in cancer." (PMID 32047266, 2020). "RASSF10 is downregulated by promoter hypermethylation in cancers and has been shown to inhibit cell proliferation; however, the molecular mechanism(s) remains poorly understood." (PMID 34224728, 2021). "Expression of RASSF10 was known to be downregulated by promoter hypermethylation across several cancers." (PMID 34224728, 2021). "Downregulation of RASSF10 expression in wide range of cancers due to promoter hypermethylation resulted in uncontrolled cell proliferation, but the mechanism(s) remains poorly understood." (PMID 34224728, 2021). "RASSF10 expression was downregulated in a wide range of cancers because of promoter hypermethylation." (PMID 34224728, 2021). "The successful pharmacological inhibition of DNA methylation restored RASSF10 expression, which we reported earlier in other cancer entities." (PMID 32047266, 2020). "Epigenetic inactivation of RASSF10 by its promoter hypermethylation is a frequent event in pathogenesis of human cancers." (PMID 32047266, 2020). "RASSF10 expression is significantly decreased in cancer cell lines vs. normal tissues (p = 4.1 × 10−62), but not ASPP2." (PMID 31817988, 2019). "We observed that methylation levels of RASSF10 correlated significantly with its reduced expression in cancer." (PMID 31817988, 2019). "In our previous work, we reported that the pharmacological inhibition (e.g., 5-Aza-2’-deoxycytidine) of DNA methylation restored RASSF10 expression in different cancer entities." (PMID 31817988, 2019). "As RASSF10 DNA promoter methylation correlates with its RNA expression across cancers, we are confident that measuring RASSF10 methylation represents its expression profile." (PMID 31817988, 2019). "This study and in our recent work we focussed on RASSF10, that exhibits CpG island hypermethylation in various cancer types." (PMID 26927176, 2016). "Like other RASSF family members, hypermethylation of the RASSF10 promoter region, which inactivates the gene, is common across several cancers." (PMID 26701853, 2016). "RASSF10 is located on chromosome 11p15.2, a region that shows frequent loss of heterozygosity (LOH) in several cancer types." (PMID 26124922, 2015). "We found RASSF2 to be methylated in three out of 43 (7%), RASSF5A in 17 out of 39 (44%, but also 43% in normal tissue), RASSF5C in two out of 26 (8%) and RASSF10 in 19 out of 84 (23%) of the cancer samples." (PMID 24252868, 2013).
cancer (continued). "Together, these reports suggest that RASSF10 might be regulating a delicate network of pathway(s) to control cell proliferation and survival during cancer progression." (PMID 34224728, 2021). "The tumor suppressor role of RASSF10 has been described in several types of cancers." (PMID 34224728, 2021). "RASSF10 is inactivated in various cancer types by DNA hypermethylation of its promoter." (PMID 32047266, 2020). "This is consistent with the observation that we neither found RASSF10 mutations in cancer nor LOH for the RASSF10 locus." (PMID 32047266, 2020). "We could show that epigenetic editing of RASSF10 is possible, and one could think of targeted therapies in the future using virally applied CRISPR-Cas9 Epigenetic Editors to patients for reactivation of e.g. hypermethylated RASSF10 specifically in cancer." (PMID 32047266, 2020). "As a causal correlation RASSF10 promoter methylation significantly correlates with decreased expression in cancer cell lines (p = 1.3 × 10−38), but not ASPP2." (PMID 31817988, 2019). "RASSF10 methylation analysis should be evaluated for its integration in present cancer screens." (PMID 31817988, 2019). "Furthermore, RASSF10 RNA levels vary in tissues, and determining the according threshold level of inactivation would have to be determined for each tissue or cancer type." (PMID 31817988, 2019). "Moreover, methylation of the RASSF10 promoter region correlates with clinicopathological characteristics and a poor prognosis in several human cancers." (PMID 26701853, 2016). "In the 20 cases of cancer samples, which RASSF10 expression was reduced, 13 cases were methylated." (PMID 25638156, 2015). "Furthermore, studies on NPM-mediated suppression of RNF2 expression and role of RASSF10 on cell cycle regulation in presence of chemotherapeutic drugs might help in designing novel cancer treatment strategies." (PMID 34224728, 2021). "However, our understanding of the function of RASSF10 in cancer is incomplete, and its role in hepatocarcinogenesis is unknown." (PMID 26701853, 2016). "However it was shown that the RASSF10 promoter was hypermethylated in cancers." (PMID 24252868, 2013). "In the present study, RASSF10 was frequently hypermethylated in HCC tissue, resulting in its low expression, as has been reported for other cancers." (PMID 26701853, 2016). "In this scenario, the vast majority of CpG island promoter methylated genes represent passenger events with only a few true cancer driving events found in each case; in this context, DZIP1, COL4A2, L3MBTL4, IRX1 and RASSF10 are named as likely candidates." (PMID 25468711, 2015). "Future studies should concentrate to confirm RASSF10 down regulation by promoter hypermethylation in MCC, as epigenetic inactivation of RASSF10 was earlier reported in different cancer cell lines and primary tumors." (PMID 24252868, 2013). "For RASSF10, there are no reported mutations and RASSF1 mutations are below 2% across primary cancers (TCGA; analyzed)." (PMID 32047266, 2020). "RASSF10 expression levels vary in cancer cell lines, but not the expression levels of ASPP2 and expression of RASSF10 and ASPP2 do not correlate." (PMID 31817988, 2019). "In human cancers, RASSF10, but not ASPP2, is epigenetically inactivated by promoter hypermethylation." (PMID 31817988, 2019). "For RASSF10 there are no genetic alterations across primary cancers (TCGA/The Cancer Genome Atlas; analyzed using)." (PMID 31817988, 2019). "Without reduction of RASSF10 expression and unmethylation were found in 7 cases of cancer tissue samples." (PMID 25638156, 2015).
RASSF10 also shares sentences with these, for which no sentence is quoted: skin cancer (2 papers); adenocarcinoma (1); childhood leukemia (1); Cirrhosis (1); dysplastic nevi (1); esophageal cancer (1); esophageal squamous cell carcinoma (1); glioma (1); head and neck cancer (1); kidney diseases (1); kidney neoplasia (1); metastatic melanoma (1); pancreatic adenocarcinoma (1); pancreatic cancer (1); polycystic kidney disease (1); prostate carcinoma (1); Renal cyst (1); Splenomegaly (1); stomach adenocarcinoma (1); viral infection (1).